GCLM (glutamate-cysteine ligase modifier subunit)
Synonyms: GLCLR
Tractability: Antibody: the Human Protein Atlas places it where antibodies can reach. PROTAC: ubiquitination databases record sites on it; its protein half-life has been measured.
Gene: Protein-coding gene on chromosome 1 (93,885,199 to 93,909,513, reverse strand). Ensembl gene ENSG00000023909.
Subcellular location (Human Protein Atlas): Cytosol; Nucleoplasm; Plasma membrane
Pathways (Reactome):
Cellular responses to stimuli: NFE2L2 regulating anti-oxidant/detoxification enzymes
Disease: Defective GCLC causes HAGGSD
Metabolism: Glutathione synthesis and recycling
Gene Ontology:
Molecular function: glutamate-cysteine ligase activity; glutamate-cysteine ligase catalytic subunit binding; protein binding; glutamate-cysteine ligase regulator activity; protein heterodimerization activity
Biological process: blood vessel diameter maintenance; glutamate metabolic process; glutathione biosynthetic process; response to oxidative stress; response to xenobiotic stimulus; cellular response to fibroblast growth factor stimulus; cellular response to follicle-stimulating hormone stimulus; cellular response to glucose stimulus; cellular response to hepatocyte growth factor stimulus; cellular response to thyroxine stimulus; hepatic stellate cell activation; negative regulation of neuron apoptotic process; response to activity; response to human chorionic gonadotropin; response to nitrosative stress; response to nutrient
Cellular component: glutamate-cysteine ligase complex; cytosol
Genetic constraint (gnomAD): Loss-of-function variants: 8 observed, 8.47 expected, observed/expected ratio (o/e) 0.94, 90% interval 0.55 to 1.65. That is too few expected variants to judge how well the gene tolerates losing a copy. Missense variants: 86 observed, 86.36 expected, observed/expected ratio (o/e) 1, 90% interval 0.84 to 1.19. Synonymous variants: 58 observed, 38.67 expected, observed/expected ratio (o/e) 1.5, 90% interval 1.21 to 1.84.
Homologues: Orthologues: chimpanzee GCLM (100% identical), macaque GCLM (99% identical), dog GCLM (97% identical), rabbit GCLM (97% identical), mouse Gclm (96% identical), rat Gclm (96% identical), pig GCLM (95% identical), tropical clawed frog gclm (68% identical), zebrafish gclm (64% identical), Caenorhabditis elegans E01A2.1 (30% identical), Drosophila melanogaster Gclm (30% identical).
Diseases named in the same sentence as GCLM in open-access papers:
GCLM is named in the same sentence as 63 diseases in open-access papers, as found by Europe PMC text mining. Sharing a sentence is not in itself a finding about the gene and the disease. The quoted sentences say what the papers report.
hepatocellular carcinoma (7 papers, 2021 to 2025). A malignant tumor that arises from hepatocytes. "In mouse hepatoma cells, tert-butylhydroquinone elicited oxidative stress and maximally induced gene expression of GCLM 10-fold, and that of GCLC 2-fold." (PMID 34445563, 2021). "HPA analysis of protein expression showed that PRDX6, GCLM, HTATIP2, NOL10, KIF18A, RAP2A and GDI2 were highly expressed in the hepatocellular carcinoma tissues compared with normal control tissues." (PMID 34760691, 2021). "Moreover, studies have reported that GCLC mRNA levels and GSH expression levels were elevated in hepatocellular carcinoma cells, however, the expression of GCLM was not any altered in hepatocellular carcinoma cells." (PMID 40651948, 2025). "To test the role of NO on glutathione, we incubated human hepatocellular carcinoma derived Huh7 cells with NO donor S-nitroso-N-acetylpenicillamine (SNAP) versus vehicle (DMSO) control and observed a significant increase in mRNA expression of both GCL subunits, GCLC and GCLM." (PMID 38198573, 2024).
breast cancer (6 papers, 2019 to 2025). A primary or metastatic malignant neoplasm involving the breast. "NRF2 knockdown had a pronounced effect on gene expression in MDA-MB-436 breast cancer cells, notably reducing multiple anti-ferroptosis genes, including SLC7A11, NQO1, TXNRD1, GCLM, and AKR1C1." (PMID 40867343, 2025). "Chemotherapy in breast cancer induces HIF1α-dependent glutathione biosynthesis by enhancing the expression of the cystine transporter xCT (SLC7A11) and the regulatory subunit of glutamate-cysteine ligase (GCLM)." (PMID 32914752, 2020).
diabetes (5 papers, 2017 to 2026). "Our findings suggest that diabetes-overexpressed miR-10b disrupts redox balance by targeting GCLM and LANCL1, which potentially leads to increased oxidative stress and cellular vulnerability in diabetic corneas." (PMID 41115935, 2026). "GCLc and GCLm are the main enzymes that catalyse glutathione synthesis, which has been shown to decline with the progression of various diseases, such as cancer, obesity, diabetes, neurodegenerative diseases, and age-related macular degeneration." (PMID 28146074, 2017). "We observed that, along with the reduced Nrf2 activation in diabetes, there was also a decrease in the content of GSH and protein expression of xCT, GCLM, and GPX4 (seen as a decrease in overall tissue immunopositivity and protein content)." (PMID 36012572, 2022).
lung carcinoma (5 papers, 2019 to 2025). "Given the downregulation of CBS, GCLC, and GCLM in DDX3X-deficient lung cancer cells, we then questioned which enzyme primarily mediates the effects of DDX3X inhibition." (PMID 40885716, 2025).
liver disease (3 papers, 2019 to 2025). "Moreover, Lira significantly upregulated ferroptosis-related proteins, including ACSL1, GCLM, and GCLC, indicating enhanced glutathione production, which protects cells from ferroptosis, a lipid peroxidation-related cell death process associated with liver disease." (PMID 41377138, 2025).
liver fibrosis (3 papers, 2023 to 2025). "Long-term ingestion of APAP can induce liver fibrosis, while andrographolide has been shown to alleviate APAP-induced liver fibrosis in mice by activating Nrf2 and upregulating the expression of downstream genes glutamate-cysteine ligase (GCLC and GCLM) and heme oxygenase-1 (HO-1)." (PMID 40959446, 2025). "In contrast, the expressions of GCLC, GCLM, NQO1, and HO-1 in the liver of the model group were significantly increased by YJSB, suggesting that YJSB might improve the antioxidant capacity of the redox system in rats, reduce oxidative stress, and interfere with the development of hepatic fibrosis." (PMID 37229248, 2023).
melanoma (3 papers, 2018 to 2022). A malignant, usually aggressive tumor composed of atypical, neoplastic melanocytes. "Consistent with previous reports that associated the Nrf2 pathway with SFN-induced chemoprevention, we found that the Nrf2 target genes HMOX1, TXNRD1, GCLC, GCLM, AKR1B10 and G6PD were upregulated after melanoma treatment." (PMID 28864908, 2018). "Moreover, ERU increased the expression of antioxidant target genes, such as GCLC, GCLM and HMOX-1, suggesting that the modulation of ROS production and the impairment of mitochondrial activity in the melanoma cells were among the contributing factors, which supported the antitumor activity of ERU." (PMID 36670903, 2022). "However, it has also been reported that the expressions of GCLM and GCLC do not correlate with NRF2 expression in melanoma." (PMID 35326683, 2022). "It has also been determined that melanomas with higher expressions of GCLC correlate with a better prognosis in patients; however, GCLC expression does not necessarily indicate changes in GCL activity, as GCLM expression plays a larger role in controlling the function of GCL." (PMID 35326683, 2022).
Sepsis (3 papers, 2020 to 2025). Sepsis is defined as life-threatening organ dysfunction caused by a dysregulated host response to infection. "The effects of MitoQ on sepsis-mediated Nrf2, GCLM, NQO-1, and HO-1 levels were measured via real-time PCR assay." (PMID 32351320, 2020). "In particular, our results are consistent with earlier reports showing that core genes involved in these pathways—such as FTH1 and GCLM, which are related to iron homeostasis and glutathione metabolism—were found to be upregulated in sepsis, promoting iron-dependent lipid peroxidation." (PMID 41346577, 2025). "Notably, the expression patterns of core PCD-related genes in this cohort were highly consistent with those observed in the discovery datasets, with genes such as CYBB, GCLM, MAP1LC3B, NCKAP1, and PGD markedly upregulated in sepsis patients." (PMID 41346577, 2025). "Additionally, when compared to sepsis shock, we found TPSO, GCLM, CYP1B1, LCN2, and LTF were up-regulated and the FTO and CYP4V2 were down-regulated in the sepsis (p < 0.05)." (PMID 36820206, 2023).
bladder cancer (2 papers, 2022 to 2025). "A urinary bladder cancer study found GCLC, GCLM, HMOX1, and NQO1 to be upregulated." (PMID 41109135, 2025).
colorectal cancer (2 papers, 2021 to 2025). A primary or metastatic malignant neoplasm that affects the colon or rectum. "Here, the authors identify a non-canonical function of glutamate-cysteine ligase modifier (GCLM) wherein its nuclear translocation increases NF-κB activity promoting resistance to platinum-based chemotherapy in colorectal cancer." (PMID 39747101, 2025). "A recent study by Sharma P identified the Andrographis, a medicine herb, could overcome the colorectal cancer chemoresistance by regulating the ferroptosis genes, such as GCLM." (PMID 33602233, 2021).
acute liver failure (1 paper, 2024). Rapid deterioration of liver function causing encephalopathy and coagulopathy. "In APAP-induced acute liver failure patients (GSE74000), IKBKG levels decreased, and Nrf2 target genes were also repressed (i.e., HMOX1, PRDX1, TXNRD1, GPX4, GPX1, GCLC, GCLM, and NQO1)." (PMID 38505605, 2024).
alopecia (1 paper, 2023). Hair loss usually from the scalp. "In this study, SEL can significantly increase the expression of SLC7A11 and GCLM, thereby promoting the synthesis of GSH and inhibiting ferroptosis, leading to a positive effect on the treatment of alopecia." (PMID 37507872, 2023).
atherosclerosis (1 paper, 2017). A disease characterized by the build-up of fatty material and calcium deposition in the arterial wall resulting in partial or complete occlusion of the arterial lumen. "Nrf2-regulated genes such as heme oxygenase (decycling) 1 (HMOX1), peroxiredoxin (PRDX1), glutathione peroxidase 1 (GPX1), glutamate-cysteine ligase modifier subunit (GCLM) and NADPH quinine oxidoreductase 1 (NQO1) have been implicated in the protection against atherosclerosis and oxidative stress." (PMID 29113088, 2017).
breast tumors (1 paper, 2024). "Pair-wise mRNA expression correlation analysis in human breast tumors from TCGA cohort showed a positive correlation between ZMYND8 and antioxidant genes including NQO1, GPX2, GCLC, GCLM, TXNRD1, and SRXN1." (PMID 38488001, 2024).
colon adenocarcinoma (1 paper, 2022). "Various potential biomarkers for colon adenocarcinoma initiation and progression and drug targets were identified and discussed, including seven novel markers: ACSL4, ANK2, AMER3, EXOSC1, EXOSC6, GCLM, and TFRC." (PMID 35842572, 2022).
coronary artery disease (1 paper, 2026). "PBMCs from coronary artery disease (CMD) patients with CKD expressed increased amounts of the enzyme GCLM (glutamate cysteine ligase modifier), which was congruent with our finding of increased glutamate metabolism in the DM_CKD animals." (PMID 41419687, 2026).
depression (1 paper, 2025). "Once Nrf2 is activated, Keap1 is released from Nrf2 and promotes nuclear translocation of Nrf2, activating the downstream target proteins HO-1, SOD1, GCLC, and GCLM, thus playing a key role in anti-inflammatory and anti-oxidative stress activities of depression." (PMID 40308754, 2025).
esophageal cancer (1 paper, 2025). A primary or metastatic malignant neoplasm involving the esophagus. "Therefore, the regulation of the NRF2/GCLM/GPX4 pathway may provide a new therapeutic strategy for overcoming radiotherapy resistance in esophageal cancer cells." (PMID 40707557, 2025).
gastric cancer (1 paper, 2023). A primary or metastatic malignant neoplasm involving the stomach. "We evaluated the transcription levels of the genes Nrf2, GCLM, NQO1, and HMOX1 as well as the protein expression levels of these genes in gastric cancer cells to determine whether Nrf2 is involved in the CEP-induced oxidative stress mechanism." (PMID 38086844, 2023).
glomerular disease (1 paper, 2015). "The current study, for the first time, demonstrates that the glomerular disease in a mouse model of anti-GBM-GN is associated with impaired Nrf2 activation (reduced nuclear content) along with low levels of GCLc, GCLm, and GPx1." (PMID 25785827, 2015).
ischemic stroke (1 paper, 2022). A stroke disorder caused by obstruction of blood flow to the brain, due to thrombotic (local blood clot formation) or embolic (due to a blood clot or other material traveling from another site) event. "The present and previous studies clearly show that polymorphisms of key genes involved in glutathione biosynthesis such as GCLC, GCLM, GSS (glutathione synthase), and GGCT (gamma-glutamylcyclotransferase) are important contributors to the pathogenesis of ischemic stroke." (PMID 35455093, 2022).
kidney damage (1 paper, 2022). "Our study shows that PSCP treatment can improve the protein levels of Nrf2, HO-1, NQO1, and GCLM in HFD-induced kidney damage." (PMID 35223948, 2022).
lactic acidosis (1 paper, 2013). Metabolic acidosis characterized by the accumulation of lactate in the body.
malaria (1 paper, 2023). Malaria is a serious and sometimes fatal disease caused by a parasite that commonly infects a certain type of mosquito which feeds on humans. "There is strong literature evidence for ICAM1, as well as another gene identified herein, GCLM, and its associated gene, GCLC being potential molecular mediators for the pathology of malaria." (PMID 37287037, 2023).
mastitis (1 paper, 2016). Inflammation of breast tissue during lactation or postpartum due to an obstructed duct or infection. "Compared with the mastitis challenged cells, enhanced expressions of antioxidant genes HO-1, Txnrd-1, and GCLM were observed in CP-treated cells." (PMID 27433029, 2016).
ovarian carcinoma (1 paper, 2011). A malignant neoplasm originating from the surface ovarian epithelium. "We performed quantitative RT-PCR todetermine the gene expression level of glutamate-cysteine ligase (GCLM) andglutathione synthase (GSS), in the Bmi-1 siRNA transfected ovarian cancer celllines." (PMID 21445297, 2011).
pheochromocytoma (1 paper, 2025). "Then, we constructed amino acid metabolism profiles by WGCNA and LASSO regression model for investigating the impact of amino acid metabolism on pheochromocytoma pathogenesis and immunity and identified six hub genes (DDC, SYT11, GCLM, PSMB7, TYRO3, and AGMAT)." (PMID 38526709, 2025).
silicosis (1 paper, 2021). Silicosis is a respiratory disease caused by breathing in (inhaling) silica dust. "The results of western bolt showed the protein expression of NRF2, KEAP1 and GCLM in PBMCs was higher in patients with silicosis than that of healthy controls." (PMID 34517882, 2021). "Moreover, RT-qPCR analysis showed that the expression of NRF2, KEAP1 and GCLM mRNA in PBMCs from patients with silicosis was higher than that in healthy controls." (PMID 34517882, 2021).
Stroke (1 paper, 2024). Sudden impairment of blood flow to a part of the brain due to occlusion or rupture of an artery to the brain. "Other genes associated with stroke and/or VaD risk include angiotensin-converting enzyme (ACE; only stroke), alpha-1 antichymotrypsin (ACT), glutamate-cysteine ligase modifier (GCLM), endothelial nitric oxide synthase (NOS3), and brain-derived neurotrophic factor (BDNF)." (PMID 39063013, 2024).
thyroid cancer (1 paper, 2025). "Our results confirmed that a combination of IDET and taxol reduces the mRNA expression of NQO1, HO‐1, GCLM, and FTH1 in thyroid cancer cells." (PMID 41394539, 2025).
type 2 diabetes (1 paper, 2023). "Interestingly, the positive impact of NFE2L2 (gene encoding Nrf2) on the expression of the glutamate–cysteine ligase modifier subunit (GCLM) was observed only in the β-cells of individuals without type 2 diabetes, whereas no such effect was observed in diabetic samples from both datasets." (PMID 37569434, 2023).
cancer (20 papers, 2013 to 2025). A tumor composed of atypical neoplastic, often pleomorphic cells that invade other tissues. "The regulatory subunit of glutamate-cysteine ligase (GCLM) is thought to be a pro-tumor gene, and its high expression is strongly associated with poor prognosis in cancer patients." (PMID 40707557, 2025). "In some studies, high expression of GCLM has been recognized as a hallmark of cancer stem cell characterization, which further supports its important role in tumorigenesis and progression." (PMID 40707557, 2025). "Several studies have indicated that GCLM is a key gene of ferroptosis and its dysregulated expression is significantly associated with the occurrence and development of cancers." (PMID 34499616, 2021). "It's previously reported that SLC1A5, SLC7A11, and GCLM are negative regulators that restrain ferroptosis in some kinds of cancers, while the remaining SAT1 facilitates ferroptosis." (PMID 35841206, 2023). "Together, these results reveal that IL1α, IL1β and GCLM are critical downstream mediators of H3 ubiquitination signalling in cancer regulation." (PMID 28300060, 2017). "Targets of NRF2 such as glucose-6-phosphate dehydrogenase (G6PD) and glutamate–cysteine ligase complex modifier subunit (GCLM) have prominent roles in promoting cancer cell survival by neutralizing the toxic effects of oxidative stress." (PMID 26890145, 2016). "It has been shown that curcumin activated NRF2 in several cell types and exerted a cytoprotective effect through transcriptional induction of phase II enzymes, such as glutathione transferase, NQO1, HMOX-1, GCLC, and GCLM in certain human cancers, skin lesions, and neurodegenerative diseases." (PMID 23710286, 2013). "Hence, targeting this newly identified signaling pathway, such as NEDD4, Gcn5 or their transcriptional targets including IL1α, IL1β and GCLM may be promising approaches for cancer therapy." (PMID 28300060, 2017). "The results showed that higher GCLM expression showed a worse prognosis in nine different cancers; In the two cancers, COAD and KIRC, GCLM existed as a protective factor and showed a better prognosis." (PMID 40707557, 2025). "In this study, we further observed the downregulation of NRF2 target genes, namely ABCG2, GCLM, and SLC1A1, which are involved in ferroptosis regulation, only in HSC2 cancer cells." (PMID 39857335, 2024). "Consistent with our prior observations, and those of others, that eprenetapopt triggers GSH depletion in cancer cells, the CRISPRko screen identified genes involved in GSH synthesis, SLC7A11 and GCLM, while GCLC was the top enriched gene in the CRISPRa screen." (PMID 36103522, 2022).